THSD7A (thrombospondin type 1 domain containing 7A)
Diseases named in the same sentence as THSD7A in open-access papers (continued):
Sharing a sentence is not in itself a finding about the gene and the disease.
gastric cancer (continued). "The current study evaluated the IC50 values of selected chemotherapeutic agents in patients with gastric cancer in high- and low-THSD7A expression groups." (PMID 37905960, 2023). "To explore the developmental trajectory of THSD7A-related endothelial cells, we first isolated the endothelial cell subpopulations in gastric cancer and normal gastric tissues, including 802 endothelial cells." (PMID 37905960, 2023). "With respect to race and the characteristics of histological subtypes, the expression of THSD7A was highest in Caucasian patients with gastric cancer (P<0.001) and intestinal adenocarcinoma (mucinous) subtypes (P<0.001), respectively." (PMID 37905960, 2023). "In vitro experiments confirmed that THSD7A was overexpressed in gastric cancer samples and cells, and that knocking out THSD7A significantly inhibited gastric cancer cell proliferation and invasion." (PMID 37905960, 2023). "First, THSD7A was mainly expressed in endothelial cells with gastric cancer and minimally expressed in the endothelial cells of normal gastric tissues." (PMID 37905960, 2023). "The results of the wound scratch assay indicated that the healing ability of gastric cancer cells was reduced at different periods following THSD7A gene knockout." (PMID 37905960, 2023). "THSD7A expressed in deep gastric cancer tissues was mainly distributed in the endothelial cell subpopulation." (PMID 37905960, 2023). "One patient with anti-THSD7A antibodies and THSD7A antigen in immune deposits had a gastric carcinoma." (PMID 28257452, 2017). "We used immunohistochemistry to analyze THSD7A protein levels in tissue microarrays involving 48 cases of gastric cancer and paired para-cancerous tissues and found that THSD7A protein levels were significantly higher in gastric cancer tissues than in normal gastric tissues (P<0.001)." (PMID 37905960, 2023). "Further analysis indicated that EMT mediated by THSD7A (+) endothelial cells may be an important pathway affecting gastric cancer cell proliferation and metastasis." (PMID 37905960, 2023). "Furthermore, our findings indicate that THSD7A shows potential for use as an effective prognostic biomarker for gastric cancer and a new target in the treatment of gastric cancer." (PMID 37905960, 2023). "The biological role and prognostic value of thrombospondin domain-containing 7A (THSD7A) in gastric cancer remain unclear." (PMID 37905960, 2023). "The mechanism of action and the diagnostic value of THSD7A in gastric cancer have not been fully investigated." (PMID 37905960, 2023). "Furthermore, we conducted a preliminary investigation to examine the impact of inhibiting THSD7A on the activity of gastric cancer cells." (PMID 37905960, 2023). "THSD7A expression was significantly increased in gastric cancer samples." (PMID 37905960, 2023). "Furthermore, we anticipate investigating the protein-level expression levels of THSD7A in gastric cancer cells, as well as its interference in mice tumor models." (PMID 37905960, 2023). "However, reports on the correlation between THSD7A expression and gastric cancer remain scant, indicating the need for further exploration." (PMID 37905960, 2023). "The findings of the study indicated that the TIDE score of the group with high expression of THSD7A was notably greater than that of the group with low expression, which indicated that immunotherapy may be less successful in gastric cancer patients with elevated THSD7A expression." (PMID 37905960, 2023). "THSD7A overexpression may be a unique prognostic marker and therapeutic target in gastric cancer." (PMID 37905960, 2023). "Following this, we conducted a survival study in gastric cancer patients by integrating the expression of TMB and THSD7A." (PMID 37905960, 2023).
gastric cancer (continued). "Finally, the nomogram constructed by integrating the THSD7A expression profile and the clinical information of gastric cancer showed that THSD7A expression may play a good predictive role in gastric cancer, the reliability of which was confirmed by the calibration curve." (PMID 37905960, 2023). "The findings revealed that patients with gastric cancer who belonged to the high TMB group and the low expression THSD7A group had the most favorable prognosis in terms of survival." (PMID 37905960, 2023). "qRT-PCR analysis showed that THSD7A was significantly upregulated in gastric cancer cells (MKN-45 and HGC-27) compared with normal gastric cells, with THSD7A being most significantly expressed in the HGC-27 cells." (PMID 37905960, 2023). "An examination of bulk sequencing data from the TCGA-STAD and GEO databases indicated that THSD7A was highly expressed in gastric cancer tissues compared to non-cancerous tissue samples." (PMID 37905960, 2023). "The Kaplan–Meier Plotter tool validated the finding that patients with gastric cancer and low THSD7A expression had higher OS (P<0.001), first progression survival (FPS; P<0.001), and post-progression survival (PPS; P<0.001), compared with those with high THSD7A expression." (PMID 37905960, 2023). "Consequently, the findings may not comprehensively represent the impact of inhibiting THSD7A on gastric cancer." (PMID 37905960, 2023). "Although the expression of THSD7A in the normal group was lower than that in patients with gastric cancer who were not infected with Helicobacter pylori (P<0.001), it was not different from that in H. pylori-infected patients with gastric cancer, which may be attributed to the small sample size." (PMID 37905960, 2023).
Hypoalbuminemia (3 papers, 2019 to 2025). The concentration of albumin in the blood circulation is below the lower limit of normal. "Indeed, despite comparable anti-THSD7A titers, C3−/− mice, which showed an interruption of the complement cascade at the level of C3, developed lower overall proteinuria, less hypoalbuminemia, less hyperlipidemia, and less pronounced podocyte foot process effacement than WT littermate controls." (PMID 36709213, 2023).
Nephropathy (3 papers, 2016 to 2025). A nonspecific term referring to disease or damage of the kidneys. "Therefore, the detection of THSD7A provides some clues for the identification of cancer-associated nephropathy." (PMID 36248963, 2022). "We found that PLA2R and THSD7A detection discriminated MN from other nephropathies, but could not distinguish secondary from primary MN." (PMID 27634909, 2016).
osteoporosis (3 papers, 2012 to 2022). A condition of reduced bone mass, with decreased cortical thickness and a decrease in the number and size of the trabeculae of cancellous bone (but normal chemical composition), resulting in increased fracture incidence. "When rs1267369 of the SNP in THSD7A was homozygous (AA), it was one of the risk factors of osteoporosis, while when rs10851839 of the SNP of THSD4 was homozygous (AA), it was one of the protective factors of osteoporosis." (PMID 36506585, 2022).
allergic disease (2 papers, 2020 to 2023). An immune response that occurs following re-exposure to an innocuous antigen, and that requires the presence of existing antibodies against that antigen. "Recently, there have been a few reports of THSD7A-associated MN that were complicated by allergic diseases." (PMID 31705303, 2020). "Our findings indicate the necessity to examine the relationship between allergic diseases and THSD7A antibody generation." (PMID 31705303, 2020).
diabetes mellitus (2 papers, 2021 to 2025). A metabolic disorder characterized by abnormally high blood sugar levels due to diminished production of insulin or insulin resistance/desensitization. "Sensitization to podocyte THSD7A happens in the background of diabetes mellitus and chronic alcoholism, and podocytes also release IL1, causing the abnormal glycosylation of IgG4, as well as the activation of complement, so THSD7A becomes exposed, and antibodies against it become actively produced." (PMID 40076824, 2025). "Interestingly, positivity for THSD7A occurred one year after the appearance of diabetes mellitus." (PMID 40076824, 2025).
glaucoma (2 papers, 2018 to 2024). Increased pressure in the eyeball due to obstruction of the outflow of aqueous humor. "THSD7A has been previously associated in GWAS studies with four ocular traits: glaucoma, intraocular pressure, refractive error, and cataract." (PMID 38582945, 2024). "These included Angpt1, Ank, Cadm2, Fmnl2, Plce1, Thsd7a, and Tmtc2 at the novel POAG/glaucoma loci identified in the current study." (PMID 29891935, 2018).
glomerulonephritis (2 papers, 2019 to 2025). A renal disorder characterized by damage in the glomeruli. "Similar to the recently established aetiology/pathogenesis-based systems for classification and diagnosis of glomerulonephritis, further elucidation of the pathogenesis and clinical management of PLA2R- and THSD7A-associated MN may lead to revised nomenclature for MN." (PMID 30868298, 2019). "Several podocyte antigens, such as PLA2R1, THSD7A, NELL1, HTRA1, and nephrin, are the primary targets of deleterious autoantibodies in glomerulonephritis patients." (PMID 40072092, 2025).
IgA nephropathy (2 papers, 2019 to 2024). "Unlike previous publications, our report showed that, although rare, PLA2R- and THSD7A-positive cases might occur in an even rarer and possibly unique combination with IgA nephropathy." (PMID 31663595, 2019).
Kimura disease (2 papers, 2019 to 2020). "The present study also presents the first documented case of THSD7A-associated MN with comorbid Kimura’s disease (case 9), a chronic inflammatory disorder mainly involving subcutaneous tissues of the head and neck region." (PMID 30868298, 2019). "Although this is the first known case of comorbidity with confirmed THSD7A-associated MN, several reports have described a possible association of Kimura’s diseases with MN." (PMID 30868298, 2019). "Likewise, in case 9 with comorbid Kimura’s disease, neck subcutaneous tissue was negative for THSD7A (not shown)." (PMID 30868298, 2019).
lung squamous cell cancer (2 papers, 2022 to 2023). "THSD7A positivity predicts poor overall survival in female patients with squamous cell carcinoma of the lung and shows a relation to high FAK expression and FGFR1 wild type in this subgroup." (PMID 37445817, 2023). "One case with lung squamous cell cancer had positive THSD7A staining in both glomeruli and cancer cells." (PMID 36248963, 2022).
lupus nephritis (2 papers, 2019 to 2025). Glomerulonephritis in the context of systemic lupus erythematosus. "Activation of lectin complement pathway is associated with various renal diseases, including IgA vasculitis, post-streptococcal acute glomerulonephritis and lupus nephritis; however, association between THSD7A-related MN and lectin complement pathway has not been examined." (PMID 30868298, 2019).
lymph node metastasis (2 papers, 2017 to 2019). "Meanwhile, all lymph nodes of 2 patients with lymph node metastasis were detected THSD7A expression with immunohistochemical staining." (PMID 31443644, 2019). "THSD7A expression was also detected in lymph nodes of two patients with lymph node metastasis." (PMID 31443644, 2019).
neuroblastoma (2 papers, 2011 to 2016). Neuroblastoma (NB) is the most common solid, extracranial childhood tumor. "In HUVECs and SH-SY5Y neuroblastoma cells, a 210-kDa soluble form of THSD7A protein can be released, and this soluble THSD7A promotes endothelial filopodia formation and focal adhesion assembly and induces FAK-dependent signalling during angiogenesis." (PMID 26796133, 2016). "In this study, we demonstrate that full-length THSD7A is expressed in HUVEC and SH-SY5Y neuroblastoma cells, and both can release a 210 kDa soluble form of the protein." (PMID 22194972, 2011). "Therefore, we compared the THSD7A protein expression patterns in cell lysates and cultured medium from SH-SY5Y cells (a human-derived neuroblastoma cell line) to those of HUVEC by Western blot." (PMID 22194972, 2011).
Obesity (2 papers, 2017 to 2019). Accumulation of substantial excess body fat. "The locus chr16:28719857 (p-value 4.36 × 10− 6) contains genes associated with body fat percentage (APOBR) and BMI (SH2B1), and rs12154393 (p-value 3.06 × 10–6) contains THSD7A, a candidate gene for obesity." (PMID 31533690, 2019).
preeclampsia (2 papers, 2015 to 2016). Preeclampsia is a hypertensive disorder of pregnancy that is characterized by new-onset hypertension with proteinuria presenting after 20 weeks of gestation, and depending on mild or severe forms may initially present with severe headache, visual disturbances, and hyperreflexia. "The THSD7A gene has been studied much less, and bioinformatic analysis of its links with the other miR-210 targets or the known preeclampsia-associated genes provides limited information." (PMID 26796133, 2016). "In summary, the results presented extend our knowledge of the function of miR-210 and THSD7A in the human placenta, and indicate that aberrantly expressed miR-210, partly through targeting THSD7A, plays an important role in the development of the pregnancy-associated disease, preeclampsia." (PMID 26796133, 2016). "This study provides novel data on the function of THSD7A in human placental cells, and extends our knowledge of how miR-210 is involved in the development of the preeclampsia." (PMID 26796133, 2016). "The aim of this study was to determine whether miR-210 is involved in preeclampsia through its targeting of THSD7A in human placental trophoblasts." (PMID 26796133, 2016). "Several target genes of miR-210 are known to be involved in preeclampsia, such as ACVR1B16, and studies have revealed that miR-210 could repress trophoblast cell invasion via modulating KCMF117, Ephrin-A3, Homeobox-A918, and THSD7A as shown in this study." (PMID 26796133, 2016).
psoriasis (2 papers, 2016 to 2018). An autoimmune condition characterized by red, well-delineated plaques with silvery scales that are usually on the extensor surfaces and scalp. "In summary, we observed the prevalence of serum PLA2R antibodies and glomerular expression of PLA2R and THSD7A in patients with psoriasis and MN." (PMID 27876003, 2016). "The present study was the first to examine the prevalence of serum PLA2R antibodies and characterize the glomerular expression of PLA2R and THSD7A in patients with psoriasis and MN." (PMID 27876003, 2016). "We examined the prevalence of serum PLA2R antibody and characterized the expression of PLA2R and THSD7A in glomeruli in patients with MN and psoriasis." (PMID 27876003, 2016). "The lower proportion of positive serum PLA2R antibody and glomerular expression of PLA2R, negative expression of THSD7A, pathological manifestation and distribution of IgG subclasses indicated that MN was associated with psoriasis in a majority of patients." (PMID 27876003, 2016). "The prevalence of serum anti-PLA2R antibody and glomerular expression of PLA2R was significantly lower in patients with psoriasis and MN than in those with idiopathic MN, and THSD7A staining was negative, suggesting that MN is associated with psoriasis in the majority of patients." (PMID 27876003, 2016). "In the present study, we evaluated 24 cases of renal biopsy-confirmed MN in patients with psoriasis to examine the prevalence of serum PLA2R antibodies and characterize the glomerular expression of PLA2R and THSD7A." (PMID 27876003, 2016).
rectal cancer (2 papers, 2018 to 2019). A primary or metastatic malignant neoplasm that affects the rectum. "This is the first case in which pathological examination results suggested that THSD7A-associated MN was caused by rectal cancer." (PMID 30727973, 2019). "Here, we report the case of a 77-year-old male patient who was diagnosed with THSD7A-associated MN after resection of rectal cancer." (PMID 30727973, 2019). "In this report, we present the case of THSD7A-associated MN after resection of rectal cancer." (PMID 30727973, 2019). "In the rectal cancer tissue, THSD7A staining was positive, showing a mainly luminal pattern, which was reported as the staining pattern of rectal cancer." (PMID 30727973, 2019). "Additionally, we performed immunostaining for PLA2R and THSD7A of the glomeruli and rectal cancer tissues with metastatic lymph nodes to discriminate between idiopathic and secondary MN." (PMID 30727973, 2019).
brain tumor (1 paper, 2020). "Furthermore, we identified THSD7A as a novel tumor‐associated factor in the most malignant type of brain tumor." (PMID 32253832, 2020).
cerebral microbleeds (1 paper, 2017). Cerebral microbleeds are a group of pathological processes affecting the small arteries, arterioles, capillaries and venules of the brain, as detected by brain imaging techniques. "Interestingly, 30% of Fabry patients show cerebral microbleeds, which together with the downregulated Thrombospondin 1 (Thsd7a) and Thromboxane a2 receptor (Tbxa2r) can be related to a general deficit in blood coagulation pathways." (PMID 29422837, 2017).
cognitive decline (1 paper, 2024). "THSD7A protein levels were strongly to greater global AD pathology, to greater amyloid-β load and PHFtau tangle density (all p < 10−5), as well as to lower level of cognitive function at baseline (p = 0.007) and faster slopes of cognitive decline (p = 0.001)." (PMID 39169872, 2024).
colorectal tumor (1 paper, 2020). "In a cohort of breast and colorectal tumor patients, THSD7A is also expressed in breast tumor tissues (20/20, 100% patients positive) and colorectal tumor tissues (79/81, 97.5% patients positive)." (PMID 33042109, 2020).
deafness (1 paper, 2022). An inherited or acquired condition characterized by the complete loss of the ability to hear from one or both ears. "For example, there were three genes which appeared to be strongly and specifically expressed in pillar cells, Col4a4 and Col4a3, which are known deafness genes, and Thsd7a, which is a gene with high variant loads in female and all participants with self-reported hearing difficulty (cluster 2K)." (PMID 35761239, 2022).
dementia (1 paper, 2024). Loss of intellectual abilities interfering with an individual's social and occupational functions. "In zebrafish, THSD7A may have a role in the neurovasculature, and THSD7A has been related to educational attainment; in recent research using GWAS summary statistics, TMEM106B/THSD7A were reported as pleiotropically related to dementia and major depression disorder." (PMID 39169872, 2024).
diabetic nephropathy (1 paper, 2021). "Since moderate to high level proteinuria is a clinical hallmark in about 20% of patients with diabetic nephropathy but may also be caused by MN, the measurement of serum THSD7A-antibody titre was repeated four months after the first testing." (PMID 34376704, 2021).
end-stage renal failure (1 paper, 2021). "In the patient with anti-THSD7A-associated MN, who reached end-stage renal failure and was subsequently transplanted with early recurrence of MN in the graft, the anti-THSD7A antibodies were detectable both before and after transplantation." (PMID 33828546, 2021).
genitourinary cancer (1 paper, 2018). "Although the causal relationship between malignancy and THSDTA-Ab-positive MN remains unclear, screening, and monitor malignancies in THSD7A-Ab-positive MN needs to be considered, especially for gastrointestinal and genitourinary cancer." (PMID 29623759, 2018).
kidney cancer (1 paper, 2018). Primary or metastatic malignant neoplasm involving the kidney. "A Chinese study found that one patient with kidney cancer appeared positive for both PLA2R and THSD7A in the tissue staining." (PMID 29623759, 2018).